SYN1 (synapsin I)
Diseases named in the same sentence as SYN1 in open-access papers (continued):
Sharing a sentence is not in itself a finding about the gene and the disease.
Sandhoff disease (1 paper, 2012). A lysosomal disorder from the GM2 gangliosidosis family, caused by biallelic pathogenic variants in the HEXB gene, characterized by GM2 ganglioside accumulation in the nervous system and progressive central nervous system degeneration. "Constructs driven from both the Hexb and SYN1 promoters were used to create transgenic lines that were intended to compare body-wide rescue from Sandhoff disease with rescue in nervous tissues only." (PMID 23028353, 2012). "Here we characterize two novel inducible strains of transgenic Sandhoff disease mice: one expresses a construct harbouring proximal elements of the mouse Hexb promoter, its counterpart is under the control of the human Synapsin 1 gene (SYN1) promoter." (PMID 23028353, 2012).
T-cell lymphoma (1 paper, 2017). "The T-cell lymphoma was relatively more and less resistant to Syn1 and BMAP-281–18, respectively." (PMID 28322271, 2017).
infection (18 papers, 2014 to 2025). The state of being infected such as from the introduction of a foreign agent such as serum, vaccine, antigenic substance or organism. "Neuro293’s express reporter-genes through the Syn1 promoter after infection with adeno-associated viruses (AAV)." (PMID 40575147, 2025). "However, synaptic depletion and neuronal loss were more pronounced, with significant reductions in Syn1 and Rbfox3 signals detected from 140 days post infection onward." (PMID 40307956, 2025). "Altogether, these results demonstrate that infection of cell lines by Syn-1-pseudotyped viruses is differently affected by Gal-1 and that cells more prone to infection optimally respond at a lower concentration." (PMID 38140682, 2023). "Our recent results showed that Gal-1 reduced the infection of HEK293T cells by Syn-1-pseudotyped viruses." (PMID 38140682, 2023). "Again, Syn-1-pseudotyped viruses might be differently affected by their infection capacity in different tested cell lines, which would be based on the receptors with which they interact and how Gal-1 vs. Gal-3 helps bridge Syn-1 with these different receptors." (PMID 38140682, 2023). "Similarly, infection with tetO-YAP lentiviruses of neurons from mice bearing Syn1-Cre or Thy1-Cre and the R26-LSL-rtTA-IRES-EGFP reporter generated EGFP-positive yNSCs." (PMID 27641305, 2016). "Notably, the relative abundance of SYN1 and PSD95, the markers of synapse ultrastructure, were also significantly downregulated post infection." (PMID 37256871, 2023). "Our results indicate that SeVdp(ABMN) infection reprogrammed MEFs into morphologically neuron-like cells, and that these cells expressed typical neuronal markers, including β-III Tubulin, MAP2, and Synapsin I." (PMID 28978921, 2017). "Conversely, the overexpression of VASH2 by the AdVASH2 infection augmented the fusion of BeWo cells without any changes in the expression of Gcm-1, Syn-1, and Syn-2." (PMID 25184477, 2014). "After infection of Neuro-2a cells with the AAV-SynTetOff vector, the transduction efficiency of green fluorescent protein (GFP) was increased by approximately 2- and 15-fold relative to the conventional AAV vector with the human cytomegalovirus (CMV) or human synapsin I (SYN) promoter, respectively." (PMID 28060929, 2017). "Importantly, the AdVASH2 infection did not alter the expression of Gcm-1, Syn-1 and Syn-2 in BeWo cells." (PMID 25184477, 2014).
tumor (9 papers, 2010 to 2023). "In tumor biology, Syn1 has been reported as a prognostic indicator for several malignancies, as its expression levels have a strong association with tumor invasion, proliferation, and cellular adhesion." (PMID 29850393, 2018). "Recently, it has been shown that heparan sulfate from Syn-1 is an active modulator of its own shedding by epithelial and tumor cells." (PMID 30922347, 2019). "The combination of HPSE enzymatic activity and Syn-1 shedding provides a powerful tool to better understand tumor development and metastasis." (PMID 30922347, 2019). "The epithelial expression of Syn1 (Syn1E) has been studied in several tumors; its expression, which can range from overexpression to complete absence, has been related to tumor behavior." (PMID 29850393, 2018). "The significant difference in the tumor volume correlates to the in vitro efficacy of Syn1 and highlights its potent anticancer activity." (PMID 28322271, 2017). "The stromal expression of Syn1 (Syn1S) is related to alterations in fibronectin and ECM organization; additionally, its expression is associated with angiogenesis and it enhances the proliferation of endothelial cells and promotes the proliferation of tumor cells." (PMID 29850393, 2018). "Syn1 and annexin A5 are upregulated in prostate cancer (PC3) and muscle (hMYO) cell cocultures and are involved in tumor cell fusion." (PMID 35242760, 2022). "Xenograft tumor of HCT 116 showed an increased expression of neuronal genes MAP2 and SYN1, neural stemness genes CDH2, MSI1, NCAM1, SOX2/9, VIM and ZEB2, and genes for mesodermal and endodermal tissues (ACP5, AFP, DESMIN, HNF4A and KRT8)." (PMID 33468253, 2021). "For example, heparin decorations on Syndecan 1 (Syn1) are necessary for Chi3L1-mediated Syn1 interaction with the integrin αvβ3, which leads to FAK signaling and ERK1/2 activation, which promotes tumor angiogenesis." (PMID 25595947, 2015). "Syn-1 interacts with a plethora of proteins via its PDZ domains and regulates transmembrane-receptor trafficking, tumor-cell metastasis, and probably neuronal-synaptic function." (PMID 20233453, 2010). "Syn1 is also upregulated in MCF-7 luminal and MDA-MB-231 triple-negative breast cancer cell lines and about 38% of breast tumor specimens and facilitates the tumor cell fusion with endothelial cells while blocking its expression inhibits the formation of THCs." (PMID 35242760, 2022). "In contrast, the Syn1 treated mice showed no tumor formation and were alive." (PMID 28322271, 2017).
cancer (7 papers, 2013 to 2025). A tumor composed of atypical neoplastic, often pleomorphic cells that invade other tissues. "Moreover, the abnormal expression of Syn-1 was reported in several cancers and was associated with the prognosis and cancer progression, by mediating the fusion of cancer cells with endothelial cells." (PMID 38140682, 2023). "Elevated levels of Syn-1 in different tumors and its increased shedding correlated with an unfavorable prognosis for patients with malignant neoplasms." (PMID 30922347, 2019). "The hub genes identified by PPI network analysis include SYN1, CNTN2, FAIM2, MT3, and SH3GL2, which are involved in the pathogenesis of different cancers." (PMID 32328342, 2020). "First we noted that out of two cancer cell lines, PC3 cells that we found to be better donors express higher amounts of Syn1." (PMID 31776415, 2019). "The plasma obtained from patients with different types of cancer was able to elicit an upregulation of HPSE, HPSE2 and Syn-1 mRNA expression." (PMID 30922347, 2019). "It was previously shown that more aggressive tumors exhibit higher heparanase and Syn-1 expression compared to that of nonmetastatic tumors, suggesting that targeting heparanase might improve cancer treatment." (PMID 30922347, 2019).
neurodegenerative disease (5 papers, 2013 to 2023). A disorder of the central nervous system characterized by gradual and progressive loss of neural tissue and neurologic function. "The porcine SYN1 promoter was studied and evaluated for use in generating neurodegenerative disease models." (PMID 24251104, 2013).
neurodevelopmental disorder (5 papers, 2021 to 2025). A behavioral and cognitive disorder with onset during the developmental period that involves impaired or aberrant development of intellectual, motor, or social functions. "In conclusion, our study expands on the molecular spectrum of SYN1 variants and improves the clinical characterization of SYN1-related neurodevelopmental disorders." (PMID 36568968, 2022). "Pathogenic SYN1 variants are associated with variable X-linked neurodevelopmental disorders mainly affecting males." (PMID 36568968, 2022). "In the study, we reported two male patients with familial SYN1 variants related neurodevelopmental disorders from Asian population." (PMID 34243774, 2021). "In summary, this study contributes to understanding complex neurodevelopmental disorders associated with SYN1, highlighting the clinical heterogeneity of gene variants and emphasizing the necessity for comprehensive genetic analysis in elucidating the pathogenic mechanisms of such diseases." (PMID 38576531, 2024). "The newly reported data and unified analysis of the clinical and molecular features of all published carriers will refine genetic counselling and the personalization of medical care for individuals with SYN1-related neurodevelopmental disorders." (PMID 36568968, 2022). "In this study, we expand on the clinical and molecular spectrum of the SYN1-related neurodevelopmental disorders by describing 31 novel individuals harboring 22 different SYN1 variants." (PMID 36568968, 2022). "Taking previously published patients into account, the number of individuals with SYN1-related neurodevelopmental disorders for whom clinical information is available is 83 (71 males and 12 females)." (PMID 36568968, 2022). "Here, we firstly reported two male patients with SYN1-related neurodevelopmental disorder in Asian population, which added clinical evidence for the condition." (PMID 34243774, 2021). "We firstly reported two familial SYN1-related neurodevelopmental disorders in Asian pediatric patients." (PMID 34243774, 2021). "In conclusion, this is the first study about SYN1-related neurodevelopmental disorder in Asian population, which expands the genetic spectrum of the disease." (PMID 34243774, 2021). "We speculated that defects in the middle motifs of Synapsin I, including domain B, C and D, are inclined to lead to neurodevelopmental disorders in human after birth, while the possible harmfulness of variants in the other domains remain unknown." (PMID 34243774, 2021). "Hence, we reached an conclusion that SYN1-related disorder is a neurodevelopmental disorder with high clinical heterogeneity." (PMID 34243774, 2021). "All reported patients with SYN1 related neurodevelopmental disorders are from European and North American studies, but none from Asian population." (PMID 34243774, 2021).
neurological disorders (4 papers, 2020 to 2025). "Synapsin I autoantibodies, previously identified in individuals with neurological disorders, have been demonstrated to modulate synaptic transmission and influence neuronal synaptic density." (PMID 39522688, 2025). "that analyzed SYN1 autoantibodies in a cohort of patients with various psychiatric and neurological disorders, binding was detected in immunoblots in about half of all patients." (PMID 36742338, 2023). "Thus, we assessed the prevalence of SYN1 autoantibodies in mothers of a cohort of 208 pediatric patients with neurological disorders." (PMID 36742338, 2023).
psychiatric disease (4 papers, 2012 to 2019). "SYN1 has been implicated in psychiatric disorders and could be a target for their treatment." (PMID 22350622, 2012). "Because of its regulatory function for neurotransmitter release, synapsin I has been suggested to play a role in psychiatric disorders." (PMID 31231257, 2019). "Of these SYN1, SYN2, and SYN3 are all associated with psychiatric disease, and the synaptic transmission and synaptic vesicle trafficking pathway." (PMID 26399914, 2015).
brain diseases (1 paper, 2022). "Both SYN1 and MSRV proteins are more expressed in fetal than in healthy adult brain specimens, while in brain diseases their presence is also associated with neuroinflammation." (PMID 35682642, 2022).
immune dysfunctions (1 paper, 2022). "The aberrant expression of HERV elements, in particular of SYN1, SYN2, and MSRV, in ASD children might thus contribute to their immune dysfunctions and to the inflammatory and autoimmune-driven brain damage." (PMID 35682642, 2022).
SYN1 also shares sentences with these, for which no sentence is quoted: autism spectrum disorder (7 papers); memory impairment (7); developmental delay (3); vascular dementia (3); viral infections (3); amyotrophic lateral sclerosis (2); brain injury (2); dementia with Lewy bodies (2); Hyperglycemia (2); acute kidney injury (1); ameloblastoma (1); amnesia (1); anorectal malformation (1); autoimmune disease (1); behavioral disorders (1); benign meningioma (1); cardiomyopathy (1); chronic kidney disease (1); cortical dysplasia (1); Crohn disease (1); dementia (1); dental caries (1); Dystonia (1); endothelial dysfunction (1); Epileptic encephalopathy (1); food allergy (1); fragile X syndrome (1); frontotemporal dementia (1); Gaucher disease (1); GM2 gangliosidosis (1).
A further 24 diseases each share a sentence with SYN1 in 1 paper.